FOXP3 (forkhead box P3)
Diseases named in the same sentence as FOXP3 in open-access papers (continued):
Sharing a sentence is not in itself a finding about the gene and the disease.
Autoimmunity (continued). "The recruitment of CD25+, FOXP3+ T regulatory cells (T-regs) is a well-defined mechanism for controlling autoimmunity in humans and animal models." (PMID 21992116, 2011). "FoxP3+ Treg cells are believed to play a role in the occurrence of autoimmunity and in the determination of clinical recurrences." (PMID 21731726, 2011). "Earlier, we have shown that GM-CSF-exposed CD8α− DCs that express low levels of pro-inflammatory cytokines IL-12 and IL-1β can induce Foxp3+ Tregs leading to suppression of autoimmunity." (PMID 21779356, 2011). "Earlier, we have shown that mice treated with GM-CSF carry large numbers of CD8α− tolerogenic DCs with the ability to induce and/or expand antigen specific Foxp3+ Tregs and suppress autoimmunity." (PMID 21779356, 2011). "Tregs are subpopulations of T lymphocytes that express the transcription factor Foxp3 and they help maintain immunological self-tolerance in the periphery and prevent autoimmunity." (PMID 21779356, 2011). "The regulation of Th17 cells is basically mediated by CD4+CD25+FoxP3+ T reg cells which are capable of inducing anergy towards self- and alloantigens, thus playing an important role in autoimmunity." (PMID 21188205, 2010). "The higher infiltration rate of Foxp3+ cells in protected rats supports the protective role of Tregs and indicates that down-regulated autoimmunity diminished the “inviting signal” to recruit peripheral immune cells that cause disease exacerbation." (PMID 20856809, 2010). "CD4+ regulatory T cells (Tregs) bearing the Forkhead Box P3 (Foxp3) transcription factor are required to maintain immunologic homeostasis and prevent autoimmunity." (PMID 21179414, 2010). "Emerging evidence demonstrates that CD4+CD25+Foxp3+ regulatory T cells (Treg cells) play a central role in the protection of autoimmunity." (PMID 20052419, 2010). "Here we report the characterization of adaptive autoimmunity and Foxp3-based immunoregulation in the zebrafish." (PMID 20221429, 2010). "The important role of Foxp3+CD4+CD25+ Treg cells in immune homeostasis is that it controls autoimmunity throughout life." (PMID 20618924, 2010). "Here we have characterized the potential for adaptive autoimmunity and Foxp3-based immunoregulation in the zebrafish." (PMID 20221429, 2010). "Induced expression of FoxP3 confers a Treg phenotype to conventional T cells, allowing these Tregs to be used therapeutically for the prevention of autoimmunity and transplant rejection." (PMID 20384988, 2010). "Hemizygous males lack Foxp3+ cells and develop lethal autoimmunity that phenocopies the human IPEX syndrome." (PMID 19330036, 2009). "FOXP3 prevents spontaneous autoimmunity by conferring on Treg cells the transcriptional profile responsible for their immune-suppressive activity." (PMID 19956618, 2009). "There is increasing evidence that reduced Foxp3 gene expression or impaired Foxp3 function is potentially responsible for the development of autoimmunity and other diseases." (PMID 19250527, 2009). "In mice, a frame-shift mutation in the Foxp3 forkhead domain (FHD) results in the loss of the DNA-binding residues, leading to the Scurfy phenotype and lethal autoimmunity." (PMID 19924293, 2009). "Mice that are deficient in Foxp3 develop severe autoimmune diseases, and mutations of human Foxp3 gene result in immunodysregulation, polyendocrinopathy, enteropathy, X linked syndrome (IPEX), which also is characterized by severe autoimmunity." (PMID 18628982, 2008). "CD4+CD25+Foxp3+ regulatory T (Treg) cells are believed to play an important role in suppressing autoimmunity and maintaining peripheral tolerance." (PMID 18304352, 2008). "FoxP3+ regulatory T cells (Tregs) maintain immune homeostasis by suppressing excessive antiself-immunity of effector T cells (Teffs) and thereby regulate autoimmunity and inhibit antitumor immune responses." (PMID 41930720, 2026).
Autoimmunity (continued). "Mice lacking Aire and Foxp3 genes develop severe autoimmunity early in life, exhibiting a more pronounced disease phenotype than either Aire‐ or Foxp3‐deficient mice alone." (PMID 41461613, 2026). "These TFs could mediate similar functions, such as maintenance of tolerance, suppression of autoimmunity, FoxP3 expression, and restricting the development of Th1 and Th17 cells." (PMID 41301818, 2025). "Intriguingly, there seems to be a threshold of FOXP3 protein level to be functional, since Tregs fail to suppress spontaneous autoimmunity in transgenic mice harboring FOXP3 gene with manipulated 3′ untranslated region (UTR) for translating about tenfold decrease in Foxp3 protein." (PMID 39979425, 2025). "Regulatory T cells (Tregs) have been regarded as the crucial element of immune regulation, since the discovery that humans lacking Tregs due to mutation of FOXP3 develop autoimmune disorders, including severe bowel inflammation." (PMID 41465370, 2025). "Notably, genes like IFNG, CD70, TNF, and FOXP3, which are critical for effector functions or regulatory T cell (Treg) development, have been shown to undergo epigenetic dysregulation in autoimmunity in response to external triggers." (PMID 41376628, 2025). "Given that IL-2 signaling is critical for FOXP3+ regulatory T cell (Treg) maintenance, such regulatory perturbations may undermine Treg-mediated tolerance and facilitate autoimmunity." (PMID 40852720, 2025). "Regulatory CD4+ T cells (Treg) that express the lineage-specific transcription factor Forkhead box P3 (FoxP3) are essential for maintaining peripheral self-tolerance, thereby preventing and managing inflammation and autoimmunity throughout an individual’s lifespan." (PMID 40493320, 2025). "Mutations in FOXP3 in humans result in IPEX syndrome, whereas mutations in Foxp3 cause scurfy in mice, both of which are characterized by lethal autoimmunity owing to a lack of functional Tregs." (PMID 40427000, 2025). "Thus, contrary to an absolute requirement of Foxp3± Treg cells for the restraint of fatal autoimmunity, Foxp3 protein in differentiated Treg cells is largely dispensable for their suppressor function." (PMID 41062655, 2025). "Therefore, the stable expression of Foxp3 plays an important role in the balance between autoimmunity and tolerance, as well as the therapeutic effect based on Tregs." (PMID 38322264, 2024). "In this study, we examined how FOXP3+ Treg obtain IL-2 at sites of autoimmune neuroinflammation." (PMID 38378682, 2024). "FOXP3 + Tregs play a crucial role in maintaining immune tolerance and preventing autoimmunity." (PMID 38951896, 2024). "Forkhead box P3 (FOXP3) plays a critical role in the pathogenesis of autoimmune disorders." (PMID 38584670, 2024). "Indeed, several previous studies have confirmed that in CVID patients with symptoms of autoimmunization, a significant decrease in Foxp3 mRNA expression and the proportion of Treg cells in comparison to controls was observed." (PMID 38474381, 2024). "FoxP3 is the master transcription factor for Treg cells, and inherited defects in the FoxP3 gene lead to the failure of Treg development, which results in fatal autoimmunity in mice and Immune dysregulation, Polyendocrinopathy, Enteropathy, X-linked (IPEX) syndrome in humans." (PMID 38786021, 2024). "However, due to the critical role of FOXP3 in regulating autoimmunity, it cannot be directly targeted for therapy." (PMID 38806474, 2024). "Our characterization of ΔtTreg mice on the B6 background revealed neither early- or late-onset of severe morbidity nor other signs of fatal autoimmunity consistently observed in mice with complete Foxp3+ Treg cell deficiency." (PMID 38164128, 2023). "In line with this, a mutation in the Foxp3 gene in humans disrupts immunotolerance and causes immune dysregulation, polyendocrinopathy, enteropathy, an X-linked (IPEX) disease characterized by multi-organ autoimmunity." (PMID 36982782, 2023).
Autoimmunity (continued). "Recent studies reported that FAO is required for the suppressive function of Treg and the prevention of autoimmunity, while oleic acid could increase Foxp3 expression and Treg function in patients with multiple sclerosis." (PMID 37843279, 2023). "Where the role of FOXP3 regulatory T cells in inhibiting Th1 and Th17 cells is well established to be crucial for immune homeostasis, inhibition of inflammatory cytokines production and prevention of autoimmunity." (PMID 37010718, 2023). "FOXP3 deficiency results in severe multisystem autoimmunity in both mice and humans, driven by the absence of functional regulatory T cells." (PMID 37156988, 2023). "Overall, the findings from Wang and colleagues provide important insights into how Foxp3 orchestrates calcium-regulated cell-cell communication to facilitate Treg suppressive function in inflammatory diseases, cancer, and autoimmunity, which will be of strong clinical interest." (PMID 38099491, 2023). "Recent studies strongly indicate that FOXP3 exon 2 controls Treg stability and autoimmunity." (PMID 37868998, 2023). "The lack of functional Tregs is most evident in Foxp3-deficient (or scurfy) mice, with pervasive inflammation as a result of multiorgan autoimmunity." (PMID 38099494, 2023). "In our B6 scurfy colony maintained under specific-pathogen-free (SPF) conditions, approximately 50% of mice succumb to premature death by 35 days of age due to fatal autoimmunity associated with Foxp3 deficiency, and no mice live beyond 50 days." (PMID 38164128, 2023). "Dysregulation of Foxp3 expression gives rise to various autoimmune disorders, such as MS." (PMID 37894952, 2023). "It is important to consider that systemic inhibition of Foxp3 could induce autoimmunity and other immune-mediated side effects." (PMID 37766222, 2023). "CD4+ Foxp3+ Tregs played an important role in preventing autoimmunity in mice and humans." (PMID 36189304, 2022). "For example, deletion of miR-146a-5p results in a breakdown of immune tolerance and development of a fatal spontaneous autoimmune disorder, whereas Foxp3 acting together with miR-155-5p blocks key inducers of effector lineage commitment, such as Satb1 and zinc finger E-box binding homeobox." (PMID 35935991, 2022). "The circulating CD4+CXCR5+FOXP3+ Tfrs with enhanced suppressive function could alleviate autoimmunity in RA patients by reducing IgG and IgM levels, and the proportion of Tfrs was negatively correlated with the disease severity." (PMID 35474948, 2022). "CD4+FOXP3+ Treg are known for their essential role in preventing autoimmunity." (PMID 36346673, 2022). "We now know these inhibitors of autoimmunity are naïve CD4+CD25+FoxP3+Treg." (PMID 35529847, 2022). "Treg cells, expressing FOXP3, are critical to regulate both inflammation and autoimmunity." (PMID 36358608, 2022). "We also observed a slight increase in NRP1+ cells among Foxp3− Th cells in MRL mice at 20–22 weeks, which may relate to the onset of the weaker systemic autoimmunity associated with non‐LPR MRL mice." (PMID 36069030, 2022). "Therefore, epigenetic events that impair Foxp3 expression lead to disinhibition of the immune system with subsequent T-cell mediated autoimmunity." (PMID 35935991, 2022). "Regulatory CD4+ T cells (Treg) expressing the linage specific transcription factor forkhead box P3 (FoxP3) are indispensable for the maintenance of peripheral self-tolerance and thus for the prevention and control of inflammation and autoimmunity throughout entire life." (PMID 36389689, 2022). "CD4+FoxP3+ regulatory T cells (Treg) are crucial for the regulation of T cell responses in the peripheral lymphatic organs and thus for the prevention and control of autoimmunity." (PMID 36389689, 2022). "This is a subset of CD4+CD25+ T cells expressing the transcription factor Forkhead box P3 (Foxp3), which could suppress spontaneous multi-organ autoimmunity, including gastrointestinal inflammation induced by CD4+CD25− T cells." (PMID 36076980, 2022).
Autoimmunity (continued). "Creating a stable Treg cell line, such as with our IL37 OE Jurkat cells, will provide a convenient model for analyzing Treg plasticity, helping to understand the molecular mechanisms that support FOXP3 expression and aiding in the development of therapeutics for autoimmunity and cancer." (PMID 36010641, 2022). "Subsequently, numerous studies confirmed CD4+CD25+ T cells suppressed autoimmunity and that the lineage defining transcription factor Forkhead Box P3 (FOXP3) in collaboration with the nuclear factor of activated T cells (NFAT) controlled the expression of genes, which characterize Tregs." (PMID 36794233, 2022). "Importantly, B6/lpr-p2x7KO mice had low levels of serum TGF-β1, which is a predisposing factor to autoimmunity, as TGF-β1 plays a pivotal role in maintaining peripheral immune tolerance by promoting Foxp3+ Tregs." (PMID 36248812, 2022). "The major role played by Tregs is to prevent autoimmunity as evidenced by the fatal multiorgan autoimmunity in patients with IPEX (Immune dysregulation, Polyendocrinopathy, Enteropathy, X-linked) syndrome and Scurfy mice that harbor deleterious Foxp3 mutations." (PMID 36248808, 2022). "Lack of Foxp3+ Treg or loss-of-function mutations of Foxp3 results in devastating autoimmunity in humans." (PMID 36032121, 2022). "Indeed, Foxp3-expressing Tregs, which are indispensable for preventing autoimmunity, also effectively suppress tumor immunity." (PMID 36568387, 2022). "FOXP3 plays an indispensable role in preventing autoimmunity and maintaining immune stability." (PMID 35322929, 2022). "The abnormal butyrate production by microbiome is recognised as a cause of higher expression of non-functional form of FOXP3, which is associated with an enlarged risk of autoimmunity." (PMID 35631222, 2022). "The protein is regulated by the Ahr-RORγt-FOXP3 axis and has been found to be upregulated in immune cells in blood and affected tissues in several autoimmune disorders; thus it could be important in modulating inflammation." (PMID 34526996, 2021). "As opposed to human Treg cell deficiency, β cell autoimmunity has not been observed in non-autoimmune-prone mice with constitutive Foxp3 deficiency or after diphtheria toxin receptor (DTR)-mediated ablation of Foxp3+ Treg cells." (PMID 34447385, 2021). "In case of T1D, another pathway might be involved: Inhibition of EHMT2 has been shown to enhance CTLA4 and FOXP3 expression in regulatory T cells, both are markers of regulatory T cell function needed to maintain tolerance and prevent autoimmunity." (PMID 34220961, 2021). "In healthy individuals, Treg cells which were previously characterized as a homogenous cell population expressing CD4+, CD25+ and Forkhead box P3 (FoxP3+) are intimately involved in the regulation of the peripheral self-tolerance and thereby avoid autoimmunity." (PMID 33931598, 2021). "Indeed, Mst1 regulates the Foxp3 expression and Treg development/function and inhibits autoimmunity through modulating Foxo1/3 stability." (PMID 33924428, 2021). "The occurrence of multi-organ autoimmunity, early in life, in patients with FOXP3 mutations demonstrate that tTreg are non-redundant, and that no other regulatory population, e.g., Tr1 or pTreg, can complement loss of FOXP3+ tTreg." (PMID 33532929, 2021). "The concept of Foxp3+ regulatory T (Treg) cell-based therapies to interfere with β cell autoimmunity in T1D has been fueled in large part by evidence indicating that diminished Treg cell activity may contribute to disease pathogenesis." (PMID 34447385, 2021).
Autoimmunity (continued). "Indeed, genetically deleting either the CNS2 enhancer of the Foxp3 locus or Tet family proteins leads to a destabilized Treg lineage and the development of spontaneous autoimmunity and chronic inflammation." (PMID 33897710, 2021). "Peripheral Foxp3+ Treg survival and proliferation strictly depend on IL-2 and absence of IL-2 signaling in mice causes autoimmune disorders." (PMID 33496881, 2021). "Regarding the other FOXP3 variant, the -924 G > A was evaluated in some autoimmunity diseases but not in SLE." (PMID 33686190, 2021). "Peripherally induced Tregs and Tregs with unstable FOXP3 expression can lose FOXP3 expression and become inflammatory cells, which may contribute to autoimmunity." (PMID 32276410, 2020). "The RORγt and FOXP3 transcription factors may serve as biomarkers to establish threshold values for infection and autoimmunity and allow for individualized optimal prophylactic and immune reconstruction interventions." (PMID 32670274, 2020). "Forkhead box P3 (Foxp3)-positive regulatory T cells (Treg cells) are key mediators of peripheral self-tolerance that are able to actively suppress effector T cells, inhibit inflammation, and prevent autoimmunity." (PMID 32317002, 2020). "Third, BCAA could improve health through maintenance of autoimmune homeostasis, as BCAAs were shown to increase proliferation and function of Foxp3+ regulatory T (Treg) cells, which are important for prevention of autoimmunity." (PMID 30891588, 2020). "Deficiency of Foxp3 results in lack of Tregs, and causes severe systemic inflammatory diseases characterized by autoimmunity, colitis, and allergies." (PMID 32276410, 2020). "Indeed, mutations in the FOXP3 gene result in Immunodysregulation polyendocrinopathy enteropathy X-linked (IPEX) syndrome, characterized by Treg dysfunction and uncontrolled autoimmunity." (PMID 32977677, 2020). "Absence of Foxp3 in mice and FOXP3 in humans cause fatal multiple organ autoimmunity termed scurfy and IPEX syndrome, respectively." (PMID 33194927, 2020). "Such inducible Tregs, including Foxp3-positive Tregs induced in the periphery from naïve T cells, IL-10-secreting Type I Tregs, and TGFβ-secreting Th3 cells, have been shown to be able of preventing autoimmunity." (PMID 33202847, 2020). "OX40 can act as a key negative regulator of Foxp3+ Tregs and may have important clinical implications in models of transplantation and autoimmunity and in HCC." (PMID 33552954, 2020). "Moreover, other than its suppressive role on T cell-mediated inflammation, EGR2 has also been shown to control autoimmunity by regulating the function of FoxP3 independent CD4+CD25−LAG3+ Treg cells." (PMID 32646370, 2020). "Tregs are a subset of CD4+ T-cells that play a non-redundant role in the prevention of autoimmunity and is functionally dependent on the X chromosome-linked transcription factor FoxP3." (PMID 33375291, 2020). "IL21 down regulates FOXP3+ regulatory T cells leading to enhanced autoimmunity." (PMID 32116981, 2019). "As a consequence, the expansion of the CD4+ FOXP3+ Tregs due to elevated IL-2 concentrations likely reflects an attempted compensatory mechanism to regulate Teff cell hyperactivity in an inflammatory environment during these periods of flaring autoimmunity." (PMID 31781109, 2019). "Understanding the molecular underpinnings of Foxp3+ Treg cell stability and the dynamics of physiological Treg cell function will shed light into their pathological dysregulation and delineate novel therapeutic strategies to halt autoimmunity." (PMID 32117202, 2019).